SQSTM1 (sequestosome 1)
Diseases named in the same sentence as SQSTM1 in open-access papers (continued):
Sharing a sentence is not in itself a finding about the gene and the disease.
tumor (continued). "Histological analysis indicated that the expression of YAP1, TAZ, p62/SQSTM1 and vimentin was also elevated in the tumour tissues of hyperglycemic mice." (PMID 37665055, 2023). "The inflammatory microenvironment has a certain impact on tumor progression, and it can also regulate the expression of SQSTM1/p62 via the NF-κB signaling pathway." (PMID 37174639, 2023). "SQSTM1 plays an important role in tumor formation by regulating signaling pathways such as the nuclear transcription-related factor 2-antioxidant response, NF-κB and caspase 8-mediated apoptosis pathways." (PMID 37944249, 2023). "HNSCC is characterized by dysregulation of the autophagy–lysosome pathway, specifically the p62/SQSTM1 protein and overexpression of fibronectin 1 (FN1), which has been associated with poorer prognosis and higher tumor pathological grade in HNSCC patients." (PMID 37568764, 2023). "Acting as a tumor suppressor, p62/SQSTM1 promotes the removal of ubiquitinated dysfunctional mitochondria, particularly in inflammatory macrophages present within the TME." (PMID 37886241, 2023). "ROS can also regulate autophagy via the stimulation of TF such as NFκB which modulates the transcription of autophagy inducing genes like BECLIN1/ATG6 or SQSTM1/p62 in tumour cells." (PMID 37920248, 2023). "Given the prevalence of GLUL+SQSTM1+RTM cells in PDAC tumor tissues, and their interaction with CD8+T cells revealed by the cell chat analysis, it becomes apparent that a deeper exploration is warranted." (PMID 38149248, 2023). "p62/SQSTM1 and LC3 expression is associated with tumor recurrence in oral squamous cell carcinoma, whereas p62/SQSTM1-LC3 interaction increases invasiveness in lung cancer and correlates with poor prognosis." (PMID 37887330, 2023). "Inhibiting SQSTM1 T269/S272 phosphorylation using Doramapimod aggravates proteasome inhibitor-mediated cell damage and tumor suppression." (PMID 35840557, 2022). "In tumor cells, Nrf2 can be stimulated by activated PERK to form a positive feedback loop associated with p62/SQSTM1 to promote ARE expression." (PMID 35103096, 2022). "PCa CM reduced the activity of the luciferase reporter, suggesting that stromal p62 downregulation is mediated through the repression of SQSTM1 promoter by a soluble factor secreted by tumor cells." (PMID 35545049, 2022). "Elevated levels of Atg-7 and increased degradation (turnover) of LC3B-II and p62/SQSTM1 were detected, along with increased autophagosome production in tumor cells." (PMID 36077830, 2022). "We further revealed the colocalization of GBA with LC3 and SQSTM1/p62 proteins in tumor tissues from mice in the different groups by immunofluorescence assays." (PMID 36123535, 2022). "Immunofluorescence staining showed a significant increase of punctate LC3B and SQSTM1 signals in tumor tissues obtained from CUR5g-treated group as relative to control." (PMID 36316321, 2022). "Previous studies have confirmed that the five autophagy-related genes (BIRC5, SQSTM1, HDAC1, RHEB, and ATIC) are associated with tumor proliferation, apoptosis, and resistance to anticancer agents in HCC patients." (PMID 35573678, 2022). "Consistent with in vitro data, as revealed by WB assay, CUR5g increased LC3B-II and SQSTM1 levels within tumor tissues." (PMID 36316321, 2022). "In VHLnull ccRCC tumor cells, loss of VHL copy number results in hyperactivation of TBK1, which leads to increased autophagy, due to TBK1-mediated phosphorylation of p62/SQSTM1 on Ser366." (PMID 35395857, 2022). "We confirmed that administration of CPT to mice obviously induced autophagy in tumor tissues, as shown by increased LC3-II level and decreased SQSTM1/p62 level in tumor tissue lysates and massive formation of red-only puncta in tumor tissue sections." (PMID 35541921, 2022). "Treatment with hydroxychloroquine was also associated with an increased staining of tumor specimens for SQSTM1/p62, suggesting a reduced autophagy, and with a higher tumor infiltration by immune cells." (PMID 34439102, 2021).
tumor (continued). "Recent research suggests that autophagy degrades SNAI1 in cancer cells via LC3 and/or (sequestosome 1) SQSTM1, thereby inhibiting tumor progression." (PMID 33937013, 2021). "Recent studies have reported that SQSTM1 not only acts as the adaptor of autophagy but also is an oncogenic protein that regulates several pathways for tumor progression." (PMID 34830108, 2021). "Chemotherapy-induced cytotoxic aggregates promote autophagy-mediated clearance via the p62/SQSTM1-dependent mechanism to support tumor survival, thereby conferring chemoresistance." (PMID 33809137, 2021). "We found that protein levels of MAP1LC3B and SQSTM1 were higher in tumor tissues than in CTAN tissues in IDC patients." (PMID 34829743, 2021). "In the study, higher protein levels of MAP1LC3B and SQSTM1 were found in tumor tissues, and the high co-expression of MAP1LC3B and SQSTM1 was associated with tumorigenesis and better DFS." (PMID 34829743, 2021). "We found that protein levels of MAP1LC3B (4.41 ± 2.18 vs. 5.14 ± 1.84, p = 0.001) and SQSTM1 (0.51 ± 1.16 vs. 3.84 ± 2.24, p <0.001) were higher in the tumor tissue than in the CTAN tissues of IDC patients." (PMID 34829743, 2021). "Our results find higher protein levels of MAP1LC3B and cytoplasmic SQSTM1 in the tumor tissues of IDC patients." (PMID 34829743, 2021). "Elevated spontaneous tumor formation and tumor progression have been found to be accompanied by SQSTM1 accumulation." (PMID 34829743, 2021). "In the tumor-bearing vehicle-treated group, we observed a significant increase in relative transcript levels of Sqstm1, Map1lc3b, and Becn1 compared to all tumor-free groups (p < 0.0001 for all comparisons)." (PMID 33718372, 2021). "Quantification of PLA signals based on the intensity of PLA puncta and percentage of SQSTM1/LC3B complex-positive tumor cells revealed higher levels of SQSTM1/LC3B protein complexes in LUSCs than in LUADs." (PMID 34483138, 2021). "In this study, we compare protein levels of both MAP1LC3B and SQSTM1 between tumor tissues and corresponding tumor adjacent normal (CTAN) tissues in IDC patients." (PMID 34829743, 2021). "Risk scores were correlated with tumor stage; BMF was associated with age, gender, grade, and stage; PPP2R5B and LGALS3 were correlated with stage; SQSTM1 was associated with age and gender; while TOP2A was correlated with grade and stage." (PMID 33712023, 2021). "Co-immunofluorescence staining also showed that tumor cells with accumulated SQSTM1 were also devoid of both nuclear and cytosolic HMGB1." (PMID 32382012, 2020). "SQSTM1, which in our study was significantly upregulated by miR-218, is a useful indicator of autophagy—it accumulates in autophagic-defective tumor cells and decreases when autophagy is completed." (PMID 31948068, 2020). "Research has also found that quinacrine induces autophagic and apoptotic cell death and suppressed tumor growth in ovarian cancer by downregulating p62/SQSTM1." (PMID 33028364, 2020). "We describe a clinical case of using plasmid DNA, encoding р62/SQSTM1 protein, Elenagen, in a patient with metastatic TNBC, whose tumor was progressing after treatment with multiple lines of chemotherapy." (PMID 32076489, 2020). "The mRNA expression of SQSTM1/p62 was upregulated in 18 out of 22 (81.8%) human CRC tissues compared with the adjacent non‐tumour tissues as determined by RT‐qPCR (P < 0.001)." (PMID 30793399, 2019). "Autophagy eliminates Sequestosome-1(SQSTM1)-mediated spontaneous tumorigenesis and functions as a tumor suppressor during cancer development." (PMID 31159487, 2019). "Accumulating evidence strongly suggests that p62 (also known as sequestosome 1) is involved in metabolic reprogramming of activated fibroblasts in fibrosis and tumor stroma." (PMID 31067787, 2019). "In summary, gefitinib and AZD9291 impaired lysosomal function owing to their intrinsic alkalinity, thereby blocking autophagic degradation and resulting in the accumulation of tumor-promoting SQSTM1." (PMID 31637005, 2019).
tumor (continued). "Our present data show that, at three subsites of OSCC, cytoplasmic SQSTM1 protein expression in TAN tissue was significantly lower than that in tumor tissue." (PMID 30477228, 2018). "Our results show that both MAP1LC3B and cytoplasmic SQSTM1 were elevated in tumor tissues in three subsites of OSCC compared with that in adjacent normal tissues." (PMID 30477228, 2018). "SQSTM1 expression was positively correlated with MAP1LC3B expression in tumor tissues of patients with BMSCC." (PMID 30477228, 2018). "First, the expression levels of MAP1LC3B and SQSTM1 were higher in tumor tissues than in adjacent normal tissues at three subsites—BMSCC, TSCC and LSCC." (PMID 30477228, 2018). "The autophagy marker microtubule-associated protein light chain 3B (MAP1LC3B) and adaptor sequestosome 1(SQSTM1) are widely used proteins to evaluate autophagy in tumor tissues." (PMID 30477228, 2018). "The connection between unappropriated autophagy and SQSTM1/p62 accumulation and tumor formation was also detected when SQSTM1/p62-/- mice were protected from Ras-induced lung carcinomas compared with wt animals." (PMID 29783720, 2018). "To the best of our knowledge, we are the first group to report that the correlation of MAP1LC3B and SQSTM1 with clinicopathological outcomes at certain subsites using the largest cohort, comprising 498 paired tumor and adjacent normal tissues of OSCC." (PMID 30477228, 2018). "For SQSTM1, its expression level was significantly upregulated in tumor group (SMD = 1.19, 95% CI: 1.00–1.37, P < 0.001)." (PMID 29707114, 2018). "In this study, we compared the MAP1LC3B and SQSTM1 protein levels in tumor tissues and adjacent normal tissues in three major subsites of OSCC, including BMSCC, TSCC and LSCC." (PMID 30477228, 2018). "This tumor suppressive function has been suggested to be dependent on selective autophagy degradation and its interaction with SQSTM1." (PMID 28915569, 2017). "Next, we examined the expression of MARCH2, Ki-67, SQSTM1 and cleaved caspase-3 in the xenograft tumor sections." (PMID 28749466, 2017). "Simultaneously, TMEM74 overexpression contributed to the increase in free GFP levels and the upregulation of SQSTM1 degradation in the three tumor cell lines." (PMID 29048433, 2017). "Immunohistochemistry showed low levels of miR-20a targets (BECN1, ATG16L1 and SQSTM1) in tumor tissues." (PMID 28628113, 2017). "Especially, p62/SQSTM1, one of autophagy-specific substrates, is degraded through the autophagy-lysosomal pathway, while p62/SQSTM1 accumulation often enhances tumor growth and other pathological conditions." (PMID 28537904, 2017). "Simulating glutaminolysis by artificially increasing the intracellular levels of αKG is known to induce tumor cell death in vivo (10Oncogene), although the involvement of mTORC1 and SQSTM1/p62 in this phenotype remains elusive." (PMID 28616576, 2017). "SQSTM1 (Sequestosome 1), also known as p62, is a multifunctional adaptor protein involved in processes such as autophagy, oxidative stress responses, protein degradation, inflammation, and tumor progression." (PMID 41523581, 2026). "Furthermore, high levels of SQSTM1 encourage high activity of the NF-κB pathway, mediating prosurvival signals in a way that further promotes tumor development." (PMID 39941813, 2025). "In accordance with this, an accumulation of p62/SQSTM1 has been observed in many human tumors, which could represent not only a biomarker but also evidence of an altered autophagy in tumor cells." (PMID 39996745, 2025). "Concurrently, autophagy-related genes such as MAP1LC3B and SQSTM1 were elevated, indicating enhanced autophagic activity that may facilitate cellular adaptation to microenvironmental stressors and contribute to tumor progression." (PMID 41394809, 2025).
tumor (continued). "Mechanistically, ALO inhibits the fusion of autophagosomes with lysosomes and the autophagic flux, leading to the accumulation of sequestosome‐1 (SQSTM1) and production of reactive oxygen species (ROS), thereby inducing tumor cell apoptosis and preventing tumor growth." (PMID 39166458, 2024). "The physiological level of autophagy prevents cancer progression by suppressing benign tumour growth, but some oncogenic viruses of the Herpesviridae family induce cancer by dysregulating autophagy, typically exhibiting abnormal accumulation of p62/SQSTM1." (PMID 36653801, 2023). "Moreover, it has been assessed that SQSTM1/p62, as a tumor oncogene, is frequently abnormally upregulated and engaged in the acquired malignancy of gastrointestinal tumors, such as CRC." (PMID 37373349, 2023). "Therefore, we searched for drugs effectively targeting SQSTM1/p62 and found that the anti-tumor drug DDP significantly reduced the expression level of SQSTM1/p62 in SQSTM1 WT HepG2 cells at 2.5–10 μM." (PMID 37174639, 2023). "Amounts of phosphorylated p62/Sqstm1 build up in HCV-positive tumor areas." (PMID 37946175, 2023). "First, we analyzed lysates of drug-treated 2D and 3D cultures and tumor xenografts with LC3b and p62 (SQSTM1) antibodies, both of which have been identified as good indicators for autophagosome formation, and the content of LC3b-II is closely correlated with the number of autophagosomes." (PMID 35887373, 2022). "However, SQSTM1/p62 acts as a tumor-promoting factor, inducing HDAC6 expression to suppress microtubule acetylation-mediated autophagy, leading to prostate cancer metastasis." (PMID 35317831, 2022). "Furthermore, the impairment of autophagy in tumor cells following metabolic stress also results in the accumulation of p62/SQSTM1, leading to increased retainment of damaged mitochondria, heightening oxidative stress and DNA damage." (PMID 35887082, 2022). "Analysis of GFP-positive stromal cells isolated by fluorescence-activated cell sorting (FACS) showed reduced Sqstm1 (coding for p62) mRNA levels in stromal cells on incubation with tumor cells, which also correlated with an increase in bona fide CAF markers, such as Tgfb1 and Sdf-1." (PMID 35545049, 2022). "However, researchers are increasingly finding that SQSTM1 has an essential and complex role in tumor progression." (PMID 35957699, 2022). "miRNA345 silences the production of KISS1, which can lead to the upregulation of proangiogenic VEGF, pro-invasive MMP9 and SLUG, EMT-related E-cadherin, autophagy-related ATG5, LC3-II, and p62/SQSTM1, to ultimately promote tumor cell adaptation and propagation in the brain." (PMID 33466236, 2021). "Moreover, protein expression levels of SQSTM1 were positively correlated with that of EGFR in tumor tissues of OSCC patients (r = 0.136, p < 0.001)." (PMID 34830108, 2021). "Overexpression of SQSTM1 gene, or abnormal aggregation and phosphorylation of SQSTM1 lead to disorder of glucose and glutamine metabolism and promote tumor development in HCV-positive HCC through persistent activation of nuclear factor erythroid 2-related factor 2 (Nrf2)." (PMID 33712023, 2021). "SQSTM1 accumulation resulting from autophagy inhibition has been detected in several cancers and may contribute to tumor progression." (PMID 34830108, 2021). "Nrf2 and p62/SQSTM1 jointly contribute to mesenchymal transition and tumour infiltration in GBM." (PMID 34804371, 2021). "Immunoblot assay showed that combination treatment clearly upregulated expressions of LC3-, Beclin-1, cleavad-caspase 7 and -PARP, and downregulated SQSTM1 expression compared to single treatment in xenograft tumor specimens, which were in consistent with the finding in vitro." (PMID 32226300, 2020). "We next analyzed whether the accumulation of SQSTM1 in tumor tissue could activate the anti-oxidative response-related NRF2 transcription factor as in non-tumor tissues." (PMID 32382012, 2020).
tumor (continued). "In addition, the tumor tissues were positive for the hepatocyte-specific marker, HNF4α, which was colocalized in the same cells that had elevated SQSTM1 and UB staining." (PMID 32382012, 2020). "Also, the mRNA levels of Map1lc3b and Sqstm1 were upregulated in tumor hosts, together with increased Ctsl1 and Lamp2 gene expression." (PMID 30823492, 2019). "The role which p62/SQSTM1 plays in cancer and tumor stroma cells is a subject of active research." (PMID 31754084, 2019). "Nevertheless, opposite effects were observed in TSCC, whereas MAP1LC3B was correlated with SQSTM1 expression in both tumor and adjacent normal tissues in LSCC, suggesting these molecules might be differentially regulated at diverse subsites of OSCC." (PMID 30477228, 2018). "With a tissue microarray comprised of 498 OSCC patients, including 181 BMSCC, 244 TSCC, and 73 LSCC patients, we found that the expression levels of MAP1LC3B and cytoplasmic SQSTM1 were elevated in the tumor tissues of three subsites compared with those in adjacent normal tissues." (PMID 30477228, 2018). "Similarly to in vitro experiments, tigecycline elevated the LC3 II level, accompanied by the down‐regulation of SQSTM1/p62 in tumour tissue in tigecycline‐treated group, indicating that autophagy does occur in tigecycline‐treated MM cells in vivo." (PMID 30247801, 2018). "We further determined whether MAP1LC3B expression was correlated with SQSTM1 in tumor tissues and adjacent normal tissues in three subsites of OSCC." (PMID 30477228, 2018). "It was also shown that P62/SQSTM1, which is eliminated through autophagy, inhibits tumor growth." (PMID 27242439, 2016). "Recently, optineurin has been reported to participate in the autophagic degradation of damaged mitochondria and to be able to functionally interact with p62/SQSTM1 to form an autophagy receptor complex that accelerates autophagic flux for the suppression of tumor growth." (PMID 26287246, 2015). "Moreover, the role of SQSTM1 in autophagy connects it to metabolic reprogramming in cancer cells, implying that it affects not just oxidative stress responses but also influences larger metabolic pathways that are crucial for tumor survival and growth." (PMID 39941813, 2025). "However, in HCC, whether SQSTM1/p62 regulates tumor migration and invasion and the mechanisms involved remain unclear." (PMID 37174639, 2023). "SQSTM1, also known as P62 protein, is one of the autophagy-related proteins, which is involved in various signal transduction processes in vivo and is degraded during autophagy and apoptosis, and the accumulation of SQSTM1 inhibits autophagy and promotes tumor progression." (PMID 35892599, 2022). "Indeed, phosphorylated SQSTM1/p62 has been shown to accumulate in the HCC tumor region, while its inhibitor may inhibit cell proliferation and resistance to anticancer agents." (PMID 32807131, 2020). "In addition, in the BGC-823 cell-mediated xenograft model, immunohistochemical staining showed increased LC3-II and ATG7 expression together with decreased SQSTM1 expression in the tumor tissues of the apatinib group compared with the expression in the tumor tissues of the control vehicle group." (PMID 32139670, 2020). "Interestingly, ablation of MAP1LC3B or SQSTM1 or both decreased tumorsphere formation and enhanced the killing effects of paclitaxel (PTX), implying that MAP1LC3B and SQSTM1 might modulate autophagy for tumor growth and drug resistance in BMSCC cells." (PMID 30477228, 2018). "SQSTM1, involved in autophagy and antioxidant response, is often overexpressed in HCC, contributing to tumor cell survival and proliferation." (PMID 40018411, 2025). "Conversely, the genes FTH1, SQSTM1, HSPA6, TSPYL2, PHLDA2, ITGAX, and DNAJA4 are expected to act as versatile protein regulators, potentially suppressing tumor cell genetic instability and promoting autophagy, apoptosis, and other forms of cell death." (PMID 40986633, 2025).